INS (insulin)
Diseases named in the same sentence as INS in open-access papers (continued):
Sharing a sentence is not in itself a finding about the gene and the disease.
Obesity (continued). "Thus, we induced obesity in rats using a long-term high-fat diet (HFD), then investigated its effects on insulin signaling and tau hyperphosphorylation." (PMID 29673239, 2018). "The state of IR in normal situations determines the compensatory increase in insulin secretion by the pancreas, which can be observed in obesity, however, not always detects the development of glycemic alterations." (PMID 29449893, 2018). "The increased amount of WAT in obesity may attribute to the increased circulating concentrations of TG, FFA, insulin, and leptin." (PMID 30558262, 2018). "Without the adjustment of obesity or BMI, we observed 148 significant associations (p < 0.05) with 39 for SBP, 45 for insulin, 1 for glucose, 14 for TG, 5 for TC, 25 for HDLC, and 19 for LDLC." (PMID 29312471, 2018). "The proportion of POMC neurons activated by insulin was dependent on the regulation of insulin receptor signaling by the phosphatase TCPTP, which is increased by fasting, degraded after feeding and elevated in diet-induced obesity." (PMID 30230471, 2018). "At the functional level, a previous report identified a significant inverse correlation between the activity of plasma erythrocyte enzyme with weight, BMI, plasma insulin, and HOMA in a case study (n = 194) and controls (n = 191) among Spanish children with obesity." (PMID 29339975, 2018). "Generalized estimating equations were used to estimate adjusted odds ratios (aOR, [95% confidence intervals, CI]) for overweight/obesity among offspring, related to IOM adherence, adjusting for pre-pregnancy BMI and mean maternal daily insulin units/kg body weight." (PMID 30559715, 2018). "Furthermore, animal models of obesity have established that fatty acid mediated alterations in TLR2 and TLR4 signaling play a central role in the establishment of insulin and leptin resistance." (PMID 30131724, 2018). "Moreover, myostatin knockout mice have significantly improved insulin sensitivity and glucose uptake, have increased peripheral tissue FAO, and are protected from diet-induced obesity." (PMID 29697773, 2018). "In the present study we found that AT, but not skeletal muscle, SIRT1 expression is decreased in obesity and is positively related to whole-body insulin sensitivity." (PMID 29417372, 2018). "Conversely, in the diet resistant phenotype, obesity does not develop and insulin sensitivity is normal." (PMID 30353684, 2018). "While many rodent studies have addressed the impacts of obesity on insulin secretion independently (reviewed in20–23), there have been none addressing the impacts of age and obesity together on weight gain, glucose tolerance, and insulin secretion." (PMID 30546031, 2018). "There were differences in fasting insulin concentrations and HOMA-IR values between children with obesity and children with normal weight in each Tanner stage evaluated; these were higher in the group of children with obesity (P < 0.001)." (PMID 30254673, 2018). "Consequently, reduction of WTAP in mice leads to protection from diet-induced obesity (DIO), thereby improving insulin sensitivity." (PMID 29866655, 2018). "Results from HUNT were similar with a stricter definition of LADA (no insulin treatment); HR was 6.63 (95% CI 3.67, 12.00) for obesity." (PMID 29589073, 2018). "Increasing prevalence of obesity is thought to contribute to the increasing incidence of RCC via several hormonal mechanisms including free estrogen, insulin and IGF-1, as well as physical damage mechanisms by lipid peroxidation, higher glomerular filtration rate and renal plasma flow." (PMID 29568408, 2018). "Aberrant control of insulin signaling through the PI3‐kinase and protein kinase B (Akt) has been demonstrated in brain tissue from human AD patients as well as in animal brains of diet‐induced obesity." (PMID 29890051, 2018). "• Insulin levels that are on the high side of normal, or that are slightly elevated, predict later obesity in children and adolescents but not in adults." (PMID 30541568, 2018).
Obesity (continued). "Distance-based Redundancy Analyses separated fecal bacterial communities with respect to markers of obesity and insulin dysregulation, as opposed to age." (PMID 30581426, 2018). "The mechanism through which these molecules exert their effects on obesity is still unclear, but these studies suggest that miRNA-regulated adipose tissue-secreted SFRP4 is related to adiposity and contributes to global insulin resistance in a paracrine and endocrine manner." (PMID 29721017, 2018). "BAIBA also has an important therapeutic role against obesity, mainly by stimulating the oxidation of fatty acids, reducing the process of lipogenesis in WAT, and attenuating inflammation and insulin resistance." (PMID 30319436, 2018). "To date, no study has compared the effects of HIIT on skeletal muscle markers of oxidative capacity, mitochondrial biogenesis, and insulin signaling of insulin resistant and non-insulin resistant individuals with obesity." (PMID 30429793, 2018). "In the sensitive phenotype, HFD leads to maternal obesity and increased plasma insulin levels without significant effects on AFV, amniotic fluid VEGF concentrations and amnion VEGF, and sFlt‐1 gene expression." (PMID 30353684, 2018). "More than two decades ago, Hotamisligil and colleagues discovered the negative impact of tumor necrosis factor α (TNFα) on insulin sensitivity in obesity." (PMID 30591653, 2018). "In fact, it was shown that under stress exposure the hypothalamic–pituitary–adrenal axis reactivity was low and no cerebral insulin suppression occurred in obesity." (PMID 29857470, 2018). "Thus, HBG feeding suppressed the appetite and improved insulin sensitivity by increasing plasma levels of PYY and GLP-1, thereby inducing resistance to obesity." (PMID 29698465, 2018). "The negative correlation between RNFL thickness and insulin resistance parameters supported the metabolic pathogenesis of retinal changes in obesity." (PMID 28739552, 2018). "Some studies have reported that oral supplementation with sucralose increases plasma levels of GIP and insulin in patients with obesity, which suggests that the chronic use of nonnutritive sweeteners can develop a state of insulin resistance." (PMID 29854725, 2018). "Besides its effects to induce insulin secretion upon glucose administration and to regulate fatty acid metabolism, GIP was recently found to be an obesity-promoting factor by acting on adipocytes." (PMID 30158649, 2018). "WNT10b overexpression under the aP2-promoter displayed an obesity-protected phenotype with reduced brown and white adipose tissue, reduced weight and the mice were not insulin resistant." (PMID 29247377, 2018). "And mice lacking miR-378 are resistant to obesity and exhibit enhanced mitochondrial fatty acid metabolism and elevated oxidative capacity in insulin target tissues." (PMID 29484304, 2018). "Insulin has a suppressive effect on the expression of TLR4 and on the activity of the PU.1 transcription factor; however, the suppressive effect of the hormone would be expected to be reduced due to the insulin-action resistance related to obesity." (PMID 29601492, 2018). "There was a significant negative correlation between serum levels of obestatin and BMI, WHR, insulin, HOMAIR and it has been suggested that an increase in the rate of obesity in PCOS women may be attributed to lower obestatin levels in these individuals." (PMID 29932432, 2018). "In addition, at this dose, RSV was also effective in normalizing serum concentrations of TAG, glucose and insulin in a fasting state, indicating that RSV has an insulin-sensitizing effect in diet-induced obesity." (PMID 30441779, 2018). "Moreover, therapy of obesity and T2DM with Gly can improve insulin sensitivity, increase anti-inflammatory capacity, and normalize secretion of triacylglycerol-rich very-low-density lipoproteins from the liver." (PMID 30568717, 2018).
Obesity (continued). "Neither overweight/obesity nor gestational weight gain appear to be independent determinants of increased birth weight, insulin and leptin." (PMID 29925339, 2018). "There was no differential effect of maternal obesity on insulin concentrations, regardless of group." (PMID 28225809, 2017). "In the context of this newly identified pathway, we hypothesized that obesity can induce changes in BAT mitochondrial dynamics through Mfn2, thereby affecting energy expenditure and, through that, insulin sensitivity and glucose homeostasis." (PMID 28539390, 2017). "Based on our profiling data, we hypothesized that maintaining adipose KLB expression during diet-induced obesity would sensitize mice to endogenous, circulating FGF21, thus preventing FGF21 resistance and potentially improving insulin sensitivity." (PMID 28580290, 2017). "Exploring the link between Ch25h and “healthy” versus “diseased” states of obesity, we measured hepatic Ch25h levels in two cohorts of male C57BL/6J mice that were fed HFD and stratified according to their response to oral glucose and insulin tolerance tests." (PMID 28299341, 2017). "These animals develop T2DM spontaneously without the interference of obesity and have been widely used to understand the mechanisms of pancreatic beta cell failure in producing insulin and its short/long term complications." (PMID 29220408, 2017). "The proposal that long-term reduction of CIDEC/Fsp27 improves obesity and/or insulin sensitivity, under conditions of overnutrition, has never been tested." (PMID 27884961, 2017). "Concurrently, we identified obesity-associated changes in functional connectivity in the posterior part of the DMN, which was not influenced by intranasal insulin." (PMID 28487570, 2017). "Specifically, in animal models of obesity induced by a high-fat diet (HFD), CLA treatment not only compensates for body weight gain, but also increases fatty acid oxidation with a decrease in blood insulin concentrations." (PMID 29036761, 2017). "Hypothalamic low-grade inflammation was induced by prolonged lipopolysaccharide (LPS) exposure to investigate if central insulin resistance is induced by an inflammatory stimulus regardless of obesity." (PMID 28677618, 2017). "As previously reported, obese adolescents with fatty liver, independent of obesity, had elevated levels of insulin, triglycerides, and transaminases, along with the presence of reduced whole-body insulin sensitivity (WBISI)." (PMID 28640216, 2017). "An alternative, although not exclusive, conceptual frame links obesity to the insulin-dependent regulation of fat generation and takes note of the different metabolic pathways to degrade macronutrients, i.e. carbohydrates (CHO), fat and proteins." (PMID 28485680, 2017). "Our results showing that TXNIP deletion preserves insulin sensitivity without affecting weight gain or obesity lend further support to prior studies using TKO in HFD diet-induced and genetic obesity models." (PMID 28661427, 2017). "Our proposal was that in the absence of obesity in insulin-resistant rats, bioenergetic function and biochemical properties of the ETC as well as fat oxidation are not altered in skeletal muscle mitochondria, both SSM and IFM." (PMID 28850625, 2017). "It is important that these obese hibernators demonstrate no pathological consequences of their brief bout with obesity, simultaneously failing to develop inflammation and insulin in adipocytes by hibernation." (PMID 28884000, 2017). "Unlike with leptin or insulin, conditions such as those in oxytocin resistance are not present in obesity." (PMID 28819236, 2017). "Because of the close relation of β3-adrenoreceptor with obesity and lipolysis, besides blood pressure, the levels of other related intermediate phenotypes including BMI, FBG, fasting insulin, total cholesterol and HDLC were also compared across Trp64Arg genotypes." (PMID 28404887, 2017).
Obesity (continued). "Secondly, the GGT-mediated insulin sensitivity improvement was observed only in normal C57BL/6 mice but not in mice with metabolic diseases such as obesity or T2D." (PMID 28660214, 2017). "Moreover, brain PPAR-γ contributes to obesity and insulin sensitivity, and the interaction of ubiquitin and PPAR pathway provides a new partner for controlling insulin signaling." (PMID 28561770, 2017). "High serum levels of insulin and insulin-like growth factor 1 (IGF-1), adipose tissue dysfunction and inflammation, and nutrient-replete circulation constitute several of the mechanisms by which obesity supports malignant cell growth." (PMID 28959684, 2017). "Referred to as a decline in insulin bioavailability, IR is the main pathological change that occurs in T2DM and is also an important part in the development of many other diseases such as obesity, hypertension, and hyperlipidaemia." (PMID 28045971, 2017). "To test whether directly improving hepatic insulin sensitivity and glucose homeostasis in the background of HFD-induced obesity could lead to a reduction in FGF21 levels, we examined mice with a hepatocyte-specific knock-out of PTP1B." (PMID 28256636, 2017). "The present study demonstrates that long term Reb-A treatment does not promote obesity or alter insulin action." (PMID 28475596, 2017). "These abnormal phenotypes suggest that antiviral response directly impairs insulin sensitivity in host cells and tissues, thereby impairing glucose homeostasis independent of obesity and adipose tissue inflammation." (PMID 29254175, 2017). "Furthermore, we found a modifying impact of obesity status on these correlations (test for interaction: both P < 0.0001 for HOMA-IR and fasting insulin levels)." (PMID 28558676, 2017). "Youth, who were considered overweight by IOTF classification but not by CDC or WHO (non-agreement), exhibited less severe clinical obesity – characterized by lower levels of body fat, insulin and HOMA2-IR score." (PMID 29166889, 2017). "In view of these results, curcumin could efficiently reduce FBG and improve obesity-induced OGTT and insulin sensitivity." (PMID 29291086, 2017). "Mice lacking GIP receptor are protected against diet-induced obesity, due to higher energy expenditure, and insulin resistance." (PMID 28694840, 2017). "Therefore, we investigated the effect of CPAE on the insulin-signaling pathway in hypothalamus, using SHR.Cg-Leprcp/NDmcr (SHR/cp) rats as a model of obesity and MetS." (PMID 28684967, 2017). "It is possible that insulin synthesis fails to compensate adequately for the high secretory demands in extreme obesity." (PMID 28887444, 2017). "These high‐fat diets (HFDs) also contribute to the development of obesity, which is often, but not always, associated with T2DM, and can lead to both insulin and leptin resistance." (PMID 28638713, 2017). "In addition, adipocyte-specific SIRT1 knockout promoted PPAPγ activity and insulin sensitivity under chronic-HFD conditions and obesity." (PMID 29050301, 2017). "As described in weight-heterogeneous GDM women and in recent studies including HAPO, BCAA were higher in GDM women, implicating a predominant influence of insulin resistance as opposed to obesity." (PMID 28766127, 2017). "Our results suggest that neither increased glucocorticoid, insulin, and leptin levels, nor decreased adiponectin levels in fathers are sufficient to confer soma-to-germline information transfer in EI of obesity via the paternal lineage." (PMID 26662513, 2016). "Indeed, decreased insulinaemia leads to BAT activation and WAT fat mobilisation to increase EE, improve insulin sensitivity and protect against HFD-induced obesity." (PMID 27677764, 2016). "However, the improved insulin sensitivity in SRAKO mice is likely secondary to the attenuation of hepatic steatosis and obesity." (PMID 27759039, 2016).
Obesity (continued). "The absence of the S6K1 protein in mice protected them against obesity, enhanced β-oxidation, and improved insulin sensitivity, whereas two genetic models of obesity (mice K/KAy and ob/ob) fed with a high-fat diet showed markedly elevated S6K1 activity." (PMID 26999118, 2016). "Gestational diabetes exposed neonates had the highest values for umbilical cord blood insulin levels than not exposed or obesity exposed neonates." (PMID 27440187, 2016). "Consequently, KO mice have improved glucose tolerance and insulin sensitivity, and are more resistant to high-fat diet (HFD)-induced obesity." (PMID 27461402, 2016). "Since insulin levels and activity are related to body weight, it can be hypothesized that LPL activity is affected by obesity." (PMID 26786614, 2016). "Unfortunately other factors known to be altered in obesity like insulin itself or FFA have not been measured as our study was not designed for this unforeseen interaction of copeptin with BMI." (PMID 26578365, 2016). "Meanwhile, re-expression of POMC in this neuronal subpopulation in females corrected only food intake and insulin sensitivity but did neither increase physical activity, energy expenditure nor block the development of obesity." (PMID 27609221, 2016). "Overall this study demonstrates that early-onset obesity as a result of maternal HFD during lactation does not only dysregulate intrinsic-pulmonary STAT3-AMPKα-SOCS3, but also activate AKT/GSK3β pathway, indicative for insulin signaling." (PMID 27087690, 2016). "In mice lacking S6K1 in all tissues, resistance to diet induced insulin insensitivity and obesity were observed." (PMID 27826244, 2016). "However, we did observe a positive correlation between body mass and fasting insulin, which supports the concept that HFD-fed mice with lower endogenously produced circulating insulin also tend to have reduced obesity." (PMID 27055260, 2016). "Another group showed that mice lacking BACE1 are lean, resistant to diet-induced obesity and display increased peripheral tissue insulin sensitivity with improved whole-body glucose disposal." (PMID 27656136, 2016). "The improvement inglucose tolerance is likely to be another byproduct of obesity prevention given theknown negative correlation between obesity and insulin sensitivity." (PMID 26840707, 2016). "Here, we demonstrate that in Brandt's voles photoperiod-induced obesity did not result in glucose intolerance and insulin insensitivity." (PMID 27736740, 2016). "We found that bone marrow insulin sensitivity was not related to maternal obesity status but FBM insulin sensitivity correlated with whole body insulin sensitivity (R = 0.487, p = 0.001)." (PMID 27669153, 2016). "Another limitation is that we cannot rule out that (obesity-induced) overexpression of MCP-1 specifically during adulthood has a different effect on insulin action than permanent MCP-1 overexpression in muscle starting during embryonic development." (PMID 26661101, 2016). "First, it has been reported that the renin knockout mice are lean, insulin sensitive, and resistant to diet-induced obesity without changes in food intake due to a higher metabolic rate and gastrointestinal loss of dietary fat5." (PMID 26732252, 2016). "The hypothalamus produces a number of hormones and neuropeptides and is enriched with receptors for non-brain derived hormones like insulin and adipose tissue-derived adipokines like leptin that are related to obesity." (PMID 27845741, 2016). "While C-peptide is not an adipokine, it is used as a biomarker of insulin secretion which is altered in obesity." (PMID 27023786, 2016). "In summary, we observed that obesity in Kuwaiti adolescents was significantly related to high salivary insulin concentration but not to high salivary glucose concentration." (PMID 27069678, 2016).